KMT2A (lysine methyltransferase 2A)
Diseases named in the same sentence as KMT2A in open-access papers (continued):
Sharing a sentence is not in itself a finding about the gene and the disease.
leukemia (continued). "Furthermore, these results may suggest the possibility of treating KMT2A-rearranged MECs using azacytidine and venetoclax, as these treatments have shown promising outcomes in the treatment of KMT2A-rearranged leukemias." (PMID 38217715, 2024). "Studies demonstrating a role for histone ubiquitination in the KMT2A gene expression program, in addition to the known effect of proteasome inhibition on this mark, led us to consider the possibility that bortezomib altered the epigenetic landscape of the leukemia cells." (PMID 36781850, 2023). "Moreover, chromatin accessibility profiling of leukemia cells disrupted for cBAF (Smarcd2 knockout), MLL1 (Kmt2a knockout) or MLL4 (Kmt2d knockout) showed that these chromatin factors are required to maintain optimal accessibility at the Stat5a and Runx2 binding loci." (PMID 37580596, 2023). "KMT2A binds menin as part of a histone methyltransferase complex, and when it is involved in an oncogenic fusion, it may lead to aberrant transactivation of leukemia-promoting genes." (PMID 36966300, 2023). "Therefore, these 37 KMT2A rearrangements (#95–98) probably represent a subclass of KMT2A abnormalities for which other genetic abnormalities may account for the transformed phenotype of the leukemia cells." (PMID 37019990, 2023). "Similarly, pharmacologic inhibition of menin-lysine methyltransferase 2A (KMT2A) binding proved to be an effective antileukemic strategy in preclinical models of KMT2A related leukemias and supported clinical trials evaluating menin inhibitors as targeted therapies in acute leukemia." (PMID 35710782, 2022). "We could speculate the existence of a clone with the KMT2A/AFF1 fusion, which competes with the NRAS-mutated clone and initiates the leukemic process, and a minor, which may accelerate the development of the overt leukemia." (PMID 34575904, 2021). "Therefore, we next investigated whether the Kmt2a N-terminal interaction partner Menin was required in MN1-driven leukemia." (PMID 33542482, 2021). "In the KMT2Ar leukemia samples, the correlation between the KMT2A N-terminal and C-terminal profiles was significantly lower than in the control samples (r = 0.53 ± 0.21), and many of the wide KMT2A-bound regions showed an enriched KMT2A N-terminal signal relative to the KMT2A C terminus." (PMID 34663924, 2021). "Thus, this raises the concern that targeting the Menin/KMT2A interaction in leukemias that depend on wild type KMT2A could also negatively impact normal hematopoiesis." (PMID 33542482, 2021). "Nevertheless, the role of KMT2A in cancers other than leukemia remains largely unknown." (PMID 32436862, 2020). "Menin inhibitors are a novel class of targeted therapies under active clinical investigation for their potential in treating acute leukemias, particularly KMT2A‐rearranged and NPM1‐mutant leukemias." (PMID 40181550, 2026). "In conclusion, Cas9-mediated chromosomal translocations of the KMT2A gene in UBC HSPCs represent novel tool for studying pre-leukemia development and probably also leukemia onset ex vivo." (PMID 41145673, 2026). "In 2012, the first potent and selective Menin–KMT2A interaction inhibitor, MI2‐2, was discovered, showing activity in reducing cellular proliferation and oncogenic gene expression in KMT2A‐rearranged leukemia." (PMID 39887730, 2026). "As DOT1L emerged as an essential molecular drug target in acute leukemias harboring a KMT2A-fusion protein, small-molecule inhibitors targeting DOT1L were developed to reverse aberrantly expressed leukemic transcriptional programs in those leukemias." (PMID 40374809, 2025).
leukemia (continued). "Here, we present a novel murine KMT2A::AFF1 model, that provides key insights into KMT2A::AFF1 pre-leukemia, relevant to human disease." (PMID 40646135, 2025). "In gene set enrichment analysis (GSEA) DOT1L-ko HEL cells had lost leukemia stem cell (LSC) features, MYC-targets and the expression of KMT2A target genes." (PMID 40781484, 2025). "We also detected the signature in some patients with KMT2A::MLLT1 or KMT2A::MLLT3 rearrangements, suggesting that the signature can be broadly applicable to KMT2A rearranged leukemia." (PMID 40646135, 2025). "These murine studies suggest a multi-hit model for KMT2A-rearranged AML, consistent with findings in human leukemia." (PMID 40680841, 2025). "Herein, we demonstrate an unanticipated direct regulation of DYRK1A via oncogenic KMT2A rearrangements in ALL and a specific requirement of DYRK1A for leukemia proliferation." (PMID 40148558, 2025). "KMT2A inhibitors can potentially be used to treat other KMT2A aberrant malignancies e.g. KMT2A-PTD and KMT2A-a leukemias, which are in desperate need of improved therapies due to their dismal prognosis." (PMID 39303915, 2024). "Therefore, the knowledge of the pathological interactions between menin and KMT2A in KMT2Ar leukemias and NPM1mut AML, as well as the underlying mechanism of action analyzed above, has led to the recognition of a new promising target for therapies in this subset of leukemias." (PMID 38651453, 2024). "Chromosome translocations involving mixed lineage leukemia 1 (MLL1, also known as MLL or KMT2A) are a significant factor in approximately 70% of leukemia cases in infants and 5–10% in children and adults, with a generally unfavorable prognosis." (PMID 38671875, 2024). "It has been previously shown that disulfiram also impairs leukemia progression in KMT2A‐r AML by inhibiting the CXXC domain (Cysteine, X, X, Cysteine), a crucial DNA‐binding motif found in KMT2A fusion proteins." (PMID 39323480, 2024). "KMT2A fusions are relatively common chromosomal rearrangements seen in AML, occurring in 70–80% in infant leukemia and 5–10% in leukemias overall." (PMID 38502417, 2024). "In MLLr leukemias, the N-terminal of the COMPASS family H3K4 methyltransferase MLL1 (KMT2A) is fused with the C-terminal of any one of many fusion partners, including subunits of the DOT1L complex (DOTCOM) and the super elongation complex (SEC)." (PMID 39403928, 2024). "According to recent literature, the FDA has designated Menin‐KMT2A interaction inhibitors like SNDX‐5613 and KO‐539 as orphan drugs for the treatment of refractory/relapsed leukemia and AML, respectively." (PMID 39428967, 2024). "In KMT2Ar leukemias, DOT1L plays a vital role in sustaining the oncogenic transcriptional programs driven by KMT2A-fusion proteins." (PMID 39682203, 2024). "KMT2A rearrangements occur more often in children than in adults with AML and are particularly more frequent in infancy, accounting for around 50% of leukaemia cases in children under 2 years of age." (PMID 39280986, 2024). "Recently, CRISPR-mediated KMT2A rearrangement (KMT2Ar) in human umbilical cord blood (UCB) hematopoietic stem and progenitor cells (HSPCs) was used to model aspects of leukemia biology." (PMID 37917159, 2024). "By preserving the MENIN and DNA interaction domains, KMT2A fusion proteins are recruited to the canonical KMT2A wild-type (WT) targets, such as posterior HOX genes, in KMT2A-r leukemias." (PMID 39303915, 2024). "This cooperation between NPM1c and KMT2A sustains the transcription of key oncogenes like MEIS1 and HOX cluster genes, which are vital for maintaining the stem-cell-like state of leukemia cells." (PMID 39682203, 2024). "In NUP98‐r, KMT2A‐r, and NPM1‐mutant leukemia, all of which induce and depend on the MEIS1/HOXA transcriptional program, small molecule inhibitors that disrupt the Menin‐KMT2A interaction have demonstrated potent antileukemic effects." (PMID 39323480, 2024).
leukemia (continued). "One class of inhibitors with particular promise blocks the KMT2A-MENIN interaction, MENIN being crucial for the localization of KMT2A and KMT2A fusion proteins to key survival genes in leukemia cells." (PMID 39303915, 2024). "Alterations of the KMT2A gene (also known as mixed lineage leukemia 1, MLL1 or MLL gene) located at 11q23.3 are found in both acute lymphoblastic leukemia (ALL) and AML, making up ∼10% of all leukemia cases in all age groups." (PMID 37325571, 2023). "It is more prevalent in leukemias underpinned by drivers that confer phenotypic plasticity, particular rearrangements of the KMT2A (MLL) gene." (PMID 37474833, 2023). "Acute leukemias characterized by chromosomal translocations involving the KMT2A gene (previously known as MLL, HRX, HTRX1, or ALL1) are a highly aggressive group of leukemias with a poor prognosis." (PMID 37891368, 2023). "Translocation of 11q23 involving lysine methyltransferase 2A (KMT2A, also known as MLL) gene is one of the most frequent leukemia-defining abnormalities, which affects both lymphoid and myeloid lineages." (PMID 38026790, 2023). "Our prior pre-clinical work with AQ also demonstrated enrichment of KMT2A-rearranged and FLT3-ITD leukemias amongst AQ-responsive patient leukemia samples." (PMID 36831684, 2023). "For example, in leukemia, RUNX1-RUNX1T1 was observed in 227 patients, while KMT2A-ELL was observed in 26 patients." (PMID 37019972, 2023). "Menin interacts with lysine methyl transferase 2A KMT2A, previously known as mixed lineage leukemia 1 or the MLL1 gene and has a paradoxical oncogenic role in the proliferation of KMT2A-rearranged leukemias." (PMID 37296920, 2023). "MLL1, also known as KMT2A and a human homolog of yeast COMPASS/Set1, is a member of the mixed-lineage leukemia family of KMTs and mediates the deposition of H3K4me3 at the promoter of developmental regulators such as Hox genes." (PMID 37633334, 2023). "BET-inhibitors are effective in eliminating leukemia cells and suppressing target gene transcription in AML mouse models including those for KMT2A-r and NPM1c AML." (PMID 38174649, 2023). "Genomes with chromosomal rearrangements can also produce fusion circular RNAs (f-circRNAs) by backsplicing of chimeric transcripts, as first shown in leukemias with PML::RARα and KMT2A::MLLT3 translocations and later in solid cancers." (PMID 36585787, 2023). "AML with alterations of KMT2A gene (Lysine [K]‐specific methyltransferase 2A, also known as MLL gene), located at 11q23, accounts for 15% to 20% of all childhood leukemias and are of great interest because of their distinct clinical and biological features." (PMID 35833755, 2023). "KMT2A (MLL) rearrangements are observed in various types of pediatric and adult leukemia, but only one adult case report has so far shown KMT2A (MLL)-MLLT1 gene rearrangements in blastic plasmacytoid dendritic cell neoplasm (BPDCN)." (PMID 34996478, 2022). "While MEF2C is a well-established transcriptional dependency of KMT2A-rearranged AML, the role of MEF2D in leukemia has remained relatively unexplored." (PMID 35301220, 2022). "Although gene expression-based clustering was able to validate the IRX/HOXA axis as a substructure of KMT2A-r infant ALL, in order to reveal more refined disease subgroups, we further analyzed the same 61 infant leukemia samples with DNA methylation array." (PMID 36042201, 2022). "More recently, the combined inhibition of menin-MLL (MLL1, KMT2A) and FLT3 demonstrated a synergistic therapeutic opportunity in these leukemia subtypes." (PMID 35387132, 2022). "To further examine the ELP signal in KMT2A-driven infant B-ALL, we examined the ratio of the ELP signal over later stages of B-cell development in each leukemia subtype." (PMID 35288693, 2022). "As in infant leukemia cells, BLK was the second most upregulated gene in pediatric KMT2A/MLL-R+ ALL cells showing a 4.38-fold higher expression level than in normal hematopoietic cells (P-value < 1 × 10-8)." (PMID 36627892, 2022).
leukemia (continued). "We compared these to four other leukemias: NUTM1-rearranged infant B-ALL (n = 1), KMT2A-rearranged infant AML (n = 1), megakaryoblastic neonatal AML (n = 1) and childhood ETV6-RUNX1 B-ALL (a common subtype of standard-risk childhood B-ALL; n = 1)." (PMID 35288693, 2022). "Overall, our results show that SID7969543 represents a novel candidate agent with selective activity against KMT2A and CALM-AF10 translocated leukemia, warranting further investigation." (PMID 35127484, 2021). "Pharmacologic inhibition of the KMT2A–Menin interaction decreased colony-forming activity, induced differentiation programs in MN1-driven murine leukemia and decreased leukemic burden in a human AML xenograft carrying an MN1-ETV6 translocation." (PMID 33542482, 2021). "The HMT mixed-lineage leukaemia (MLL, also known as lysine methyltransferase 2A (KMT2A)) has the ability to catalyse mono-, di-, and, to a lesser extent, trimethylation of histone H3K4, and plays a pivotal role in haematological malignancies." (PMID 34968247, 2021). "To elucidate whether SID7969543 exerted its selective KMT2A-r leukemia cell killing effect through targeting and inhibiting its reported target, the transcription factor NR5A1, we firstly investigated whether the expression of NR5A1 was associated with the occurrence of a KMT2A rearrangement." (PMID 35127484, 2021). "Overall, pharmacologic inhibition of the Menin/KMT2A interaction decreased cell growth of both murine and human MN1-driven leukemia, with efficacy in vivo." (PMID 33542482, 2021). "The enzyme whose name derives from mixed-lineage leukemia (MLL, also known as MLL1, KMT2A, etc.)is one of six histone methyltransferases (HMTs) of the mixed-origin leukemia family." (PMID 34298959, 2021). "The protein level of KMT2A and KMT2D epigenetic regulators, and a few of their targets were found to fluctuate consistently between patients and their matched PDX leukemia." (PMID 33722259, 2021). "Leukemias with lineage switching appear to be more common in specific genetic subtypes, such as those with KMT2A (MLL) gene rearrangements." (PMID 34867958, 2021). "In several studies, mRNA-sequencing has been successfully adopted to detect gene fusions in leukemia, e.g. gene fusions in AML or KMT2A fusions in infant ALL." (PMID 32727569, 2020). "Molecular blockers can inhibit the subunits of MLL-FP complexes such as KMT2A-ENL to downregulate MYC expression, which is crucial for MLL-r leukemia." (PMID 33302406, 2020). "KMT2A (formerly known as MLL or mixed lineage leukemia)-rearranged acute leukemia, involving fusions of 11q23, is a particularly aggressive leukemia affecting approximately 15–20% of childhood AML." (PMID 32050659, 2020). "In conclusion, next to the studies of fusion proteins as oncogenic drivers of leukemias with MLL rearrangements, we stress the need of a molecular characterization of circRNAs expressed by fusion genes, KMT2A itself and its TPGs." (PMID 30815012, 2019). "As in the case of childhood leukemia, adult KMT2A-AML and KMT2A-ALL, despite a shared common gene profile, revealed also lineage-specific expression markers sufficient to segregate them according to their lineages, with no respect to the KMT2A fusion partner." (PMID 31467542, 2019). "One of the most aggressive subtypes of AML is characterized by the presence of translocation involving the mixed lineage leukemia gene (MLL, or KMT2A)." (PMID 28412727, 2017). "For example, the promyelocytic leukemia/ retinoic acid receptor α (PML/RARa) and lysine methyltransferase 2A (MLL) genes fused and then produced f-circM9 and f-circPR." (PMID 28928231, 2017). "Another highly specific, structurally distinct Menin–KMT2A interaction inhibitor, VTP50469, has also shown nanomolar‐range activity, effectively suppressing KMT2A‐target gene expression and cell proliferation in KMT2A‐rearranged leukemia models." (PMID 39887730, 2026).
leukemia (continued). "KMT2A rearrangements (KMT2A-r) are prominent drivers of aggressive acute leukemias, including acute myeloid leukemia (AML), acute lymphoblastic leukemia (ALL), and leukemias exhibiting mixed-lineage phenotypes, often referred to historically as ‘mixed lineage leukemia’." (PMID 40374809, 2025). "Given that KMT2A-R ALL is often a monoallelic balanced translocation with wild-type KMT2A and AFF1 still present in the cells, we then analyzed a ChIP-Seq data set that used human KMT2A-R leukemia cells generated via overexpression of a KMT2A-Aff1-flag construct." (PMID 40148558, 2025). "In leukemia, particularly in acute myeloid leukemia (AML) and acute lymphoblastic leukemia (ALL), the KMT2A (also known as MLL) gene undergoes translocations with a variety of partner genes, leading to the formation of oncogenic KMT2A fusion proteins." (PMID 39851492, 2025). "Multiple lines of evidence have shown that KMT2A rearrangements are acquired in pre-VDJ hematopoietic precursors in utero and, compared to other oncogenic fusions, initiate a strikingly rapid progression to leukaemia." (PMID 39941739, 2025). "Here, we induced chromosomal translocations between the KMT2A and AFF1 genes in primary human UCB HSPCs to model (t;411) leukemia and performed multiomics analyses on the resultant gene-edited BCP-ALLs in comparison with patient ALLs and normal bone marrow from healthy donors." (PMID 37917159, 2024). "Infant MLL1/KMT2A-rearranged (henceforth MLLr) leukemias are thought to be frequently, if not always, initiated already in utero." (PMID 38555405, 2024). "Small molecular inhibitors of the menin–KMT2A interaction target the central cavity of MEN1 to inhibit the MEN1-KMT2A interaction and could target a similar transcriptional dependency in other leukemia subsets, broadening their therapeutic potential." (PMID 39594699, 2024). "Rearrangements involving KMT2A and its fusion partner genes are found in precursor B-cell acute lymphoblastic leukemia (B-ALL), T-ALL, AML, myelodysplastic neoplasm (MDS), mixed-lineage (biphenotypic) leukemia (MPAL), and secondary leukemia." (PMID 39201709, 2024). "In these resistant cells, key KMT2A target genes, such as MEIS1 and HOXA, remain suppressed, and although the menin–KMT2A complex is successfully displaced from chromatin by the inhibitors, leukemia persists." (PMID 39682203, 2024). "Rearrangements involving KMT2A and its partner genes are found in precursor B-ALL, T-ALL, acute myeloid leukemia (AML), myelodysplastic syndrome (MDS), mixed lineage (biphenotypic) leukemia (MPAL), and secondary leukemia." (PMID 36979800, 2023). "Of note, specific exons (KMT2A exon 7, and AFF1 exons 2 and 7) backspliced to generate the most abundant circRNAs of these genes in normal blood cells are also used in f-circRNAs produced by leukemia cells with rearranged genomes." (PMID 36585787, 2023). "While BMP-like leukemias harbored fusion products known to drive high HOXA cluster expression, including MLLT10, KMT2A, NUP214, and direct HOXA::TCR fusions, T-specified leukemias had fusions to ZFP36L2 (involved in cell cycle control during T-cell beta selection) and TLX1/3." (PMID 37961674, 2023). "Mixed lineage leukemia 1 (MLL1), also known as KMT2A, was initially uncovered in the research of cancer and the translocation and rearrangement of the MLL1 gene sequence results in the leukemia." (PMID 36290729, 2022). "First, the ELP signal was not universally associated with KMT2A rearrangements; neither myeloid nor ambiguous lineage leukemias with KMT2A rearrangements harbored appreciable ELP signals." (PMID 35288693, 2022). "Finally, Mixed lineage leukemia protein-1 (i.e., MLL1, also known as KMT2A) is an H3-K4 methyltransferase, well known for its involvement in a plethora of chromosomal translocations occurring in leukemia." (PMID 35625569, 2022). "In leukemia, more than 10.5% of KMT2A (MLL) fusions result from CRs." (PMID 35945623, 2022).